NQO1 (NAD(P)H quinone dehydrogenase 1)
Diseases named in the same sentence as NQO1 in open-access papers (continued):
Sharing a sentence is not in itself a finding about the gene and the disease.
cancer (continued). "Upon cellular uptake by cancer cells, where NQO1 is often overexpressed, the enzyme catalyzes the self-immolative cleavage of the quinone trimethyl locks." (PMID 38675124, 2024). "Considering the characteristics of this natural quinone, β-lapachone has been developed to selectively target cancers with a specific increase in the quinone oxidoreductase NQO1." (PMID 39164783, 2024). "Because of variations in NQO1 levels in normal and cancer tissues, careful consideration in preclinical studies should be given to address drug efficacy and toxicity." (PMID 39120303, 2024). "These probes have been successfully used to differentiate between different NQO1-expressing cancer cells and normal cells." (PMID 38167027, 2024). "Only when both NQO1 and β-Lapachone are overexpressed simultaneously in cancer cells, the NGP-27 becomes activated and effectively degrades BRD4." (PMID 38773495, 2024). "NQO1 is frequently upregulated in various cancers, where its overexpression contributes to the development of drug resistance." (PMID 39534872, 2024). "Numerous human cancers express 5- to 200-fold higher levels of NQO1 than their healthy tissue counterparts." (PMID 39328407, 2024). "Nonetheless, other approaches targeting cells that express elevated levels of NRF2 targets such as NQO1 offer hope to induce oxidative cell death in cancer cells with exaggerated antioxidant defenses." (PMID 38254783, 2024). "QBMP did well in tests; it responded within 4 min and was used to measure NQO1 levels in cancer cells and a Parkinson’s disease model and preserved brain tissue at a depth of 225 μm." (PMID 39120303, 2024). "Because of the prevalent overexpression of NAD(P)H: quinone oxidoreductase isozyme 1 (NQO1) in many cancer types, an NQO1-responsive version of CyNH2, named NCyNH2, was developed to improve the specificity for targeting tumor cells." (PMID 39221221, 2024). "Inhibiting Nrf2 in cancer cells leads to decreased expression of NADPH Quinone Dehydrogenase 1 (NQO1), HO1, and ferritin heavy chain (FTH1), which promotes ferroptosis." (PMID 39061859, 2024). "The resulting abundance of NQO1 expression (up to 200-fold) in cancers and a barely detectable expression in body tissues makes it a selective marker of neoplasms." (PMID 39120303, 2024). "This dual requirement significantly improves the cell selectivity of NGP-27 as it ensures that only cancer cells with both elevated levels of NQO1 and β-Lapachone will undergo targeted protein degradation." (PMID 38773495, 2024). "Conofolidine increased oxidative stress, preceding apoptosis- and senescence-induction in most carcinoma cell lines as seen by enhanced ROS levels accompanied by increased NQO1 expression." (PMID 38893527, 2024). "In this section, the COMPARE algorithm was used to derive PCCs for the similarity in expression of chosen cancer molecular targets, NQO1 and TrxR, to compound growth inhibition across the NCI-60 cell line panel." (PMID 37446864, 2023). "Individualized treatment regimens must be developed for each cancer type, target their specific T-cell subtypes and differences in NQO1 levels." (PMID 37583897, 2023). "NQO1, the phase II enzyme that is highly expressed in various cancers, is a promising novel anticancer drug target for NQO1-positive cancers." (PMID 37570646, 2023). "Conversely, c-Fos overexpression decreased the proportion of cells at G2/M phase compared with that in NQO1-deficient RKO/pshNQO1 and MDA-MB-231/pCont cancer cells, and this effect was mitigated by knockdown of CKS1B." (PMID 36793872, 2023).
cancer (continued). "To compare the cytotoxicity levels of β-lap, DNQ, and IP-DNQ, we first assessed their lethality in two endogenous NQO1-expressing cancer cell lines: MCF-7 (breast) and A549 (NSCLC)." (PMID 38136388, 2023). "In this study, we performed the first pan-cancer and single-cell analysis to evaluate the impact of the NQO1 expression on clinicopathological parameters, immune cell infiltration, drug resistance, and prognosis." (PMID 37583897, 2023). "In order to achieve this aim, we collected data from different databases to investigate the role of NQO1 on the immune response in various cancers." (PMID 37583897, 2023). "Our findings provide novel insights into the role of NQO1/c-FOS/CKS1 signaling in cancer, highlighting an innovative avenue for anticancer therapeutic strategies targeting this pathway." (PMID 36793872, 2023). "Ionizing radiation (2-4 Gy) 27-30, cisplatin 30 and hyperthermia (41-42oC) 31,32 are reported to increase NQO1 expression in various human and animal cancer cells and sensitize cells to β-lapachone, both in vitro and in vivo." (PMID 36793872, 2023). "The development and clinical application of novel NQO1 bioactivatable drugs against cancer remain fervent areas of future research interest." (PMID 38136388, 2023). "This pattern is thought to be the favored one under anaerobic conditions, and NQO1 (NADPH: quinone oxidoreductase 1), an enzyme that is highly expressed in cancer tissues, is responsible for it." (PMID 38067602, 2023). "In fact, an interesting study showed that β-Lapachone specifically induced cell death in cancer cells with elevated endogenous levels of NQO1." (PMID 37175546, 2023). "First, experiments in vivo and in vitro are needed to verify the potential relationship between NQO1 with immune infiltration and the prognosis of cancers." (PMID 37583897, 2023). "Rationale: Overexpression of NAD(P)H:quinone oxidoreductase 1 (NQO1) is associated with tumor cell proliferation and growth in several human cancer types." (PMID 36793872, 2023). "Although NQO1 can protect normal cells from oxidative stress, it has been reported that a high expression of NQO1 at the early stages of carcinogenesis can favor cancer cell growth." (PMID 37175546, 2023). "Similar NQO1-mediated CKS1B induction was observed in other cancer cell lines, including A549 (lung), MIA PaCa-2 (pancreas), PC3 (prostate), and U87-MG (brain) cell lines." (PMID 36793872, 2023). "As a result, several studies evaluated the impact of NQO1 overexpression on tumor prognosis and its role as a potential target for cancer therapy." (PMID 37583897, 2023). "NQO1 regulation of AP-1-mediated CKS1 expression in cancer cells was further demonstrated by analyzing reporter activity of a series of deletion constructs of a CKS1B promoter containing two TREs in transient transfection assays." (PMID 36793872, 2023). "Experiments from the current study support a novel role of NQO1 in the regulation of cell cycle progression at the G2/M phase in cancer cells." (PMID 36793872, 2023). "Further, we analyzed the relationship between NQO1 mRNA expression levels and prognosis in various cancer types through Cox regression analysis." (PMID 37583897, 2023). "Gain-of-function and loss-of-function experiments were conducted to establish the effects of NQO1 on cancer cell proliferation." (PMID 36793872, 2023). "Depletion of NQO1 (RKO/pshNQO1 cells) resulted in slower proliferation of cancer cells relative to that in the control group." (PMID 36793872, 2023). "In essence, cancer cells already present in a concentration of NAD(P)H:quinone oxidoreductase 1 (NQO1) are 5- to 200-fold greater than in normal cells." (PMID 36903471, 2023). "In summary, our study demonstrates for the first time that NQO1 induces marked upregulation of CKS1 by stabilizing c-Fos protein in cancer cells, leading to accelerated cell proliferation." (PMID 36793872, 2023).
cancer (continued). "Most research has described the biological function of the NQO1 in certain types and limited samples, but a comprehensive understanding of the NQO1’s function and clinical importance at the pan-cancer level is scarce." (PMID 37583897, 2023). "In this context, investigating the correlation between NQO1 and cancer immunity holds great promise as it can offer novel insights and potential breakthroughs for developing more effective immunotherapeutic strategies." (PMID 37583897, 2023). "In this regard, the activation of the NRF2 target genes, such as HO-1 and NQO1, have been found to be involved in cancer progression." (PMID 36831129, 2023). "MRP1 is primarily involved in drug efflux in various cancer cells whereas NQO1 and SOD1 upregulation increases drug resistance making the prognosis even worse." (PMID 37305533, 2023). "The C18 acid also induced many ARE-regulated antioxidant genes in vitro, including Nqo1, and hence highlighting the potential of these unsaturated fatty acids for chemoprevention to protect from cancer and other oxidative-stress-mediated diseases." (PMID 37999377, 2023). "To assess the broader clinical relevance of NQO1 in breast cancer metastasis, we examined the relationship between NQO1 expression and cancer progression in clinical samples." (PMID 37169843, 2023). "NQO1 and TrxR, however, are over-expressed in many solid tumours and, thus, are viable molecular targets for cancer therapy." (PMID 37446864, 2023). "To further identify the transcription factor(s) that mediate CKS1B expression in cancer cells, we analyzed gene expression in NQO1-containing (RKO/pshCont) and NQO1-deficient (RKO/pshNQO1) cells." (PMID 36793872, 2023). "In conclusion, our findings indicate that IP-DNQ triggers both apoptosis and programmed necrosis in NQO1-positive cancer cells." (PMID 38136388, 2023). "NQO1 was highly expressed in cancer cells and several cells, especially DC, macrophages, neutrophils, and T cells." (PMID 37583897, 2023). "siRNA-mediated knockdown of c-Fos (sic-Fos transfection) increased the proportion of cells at G2/M phase in NQO1-expressing cancer cells compared with that in the siCont-transfected group, an effect that was rescued by reintroduction of CKS1B." (PMID 36793872, 2023). "The synthesized prodrugs were tested against NQO1-overexpressing A549 and HepG2, hypoxia-induced A549 and HepG2, and Taxol-resistant A549 human cancer cell lines." (PMID 38140069, 2023). "Collectively, these results clearly support effects of NQO1 on cell cycle progression at the G2/M phase in cancer cells." (PMID 36793872, 2023). "To further examine the potential involvement of NQO1 in the regulation of cell cycle progression, we analyzed the cell cycle dynamics of cancer cells at the single-cell level with the aid of time-lapse confocal microscopy." (PMID 36793872, 2023). "Because NQO1 is a quinone-reducing enzyme that is upregulated by Nrf2, the rationale is that this approach should selectively target cancer cells that have constitutive Nrf2 activation." (PMID 36978989, 2023). "Consistent with previous studies, our findings indicate that most cancers had higher expression levels of NQO1 compared to normal tissue." (PMID 37583897, 2023). "By exploring the intricate relationship between NQO1 and cancer immunity, we can deepen our understanding of the mechanisms underlying tumor immune escape and potentially unveil new biomarkers and therapeutic targets." (PMID 37583897, 2023). "This NQO1-mediated increase in protein stability of c-Fos further promotes expression of CKS1 in cancer cells, resulting in increased cell proliferation and radioresistance." (PMID 36793872, 2023). "This dependence creates a therapeutic opportunity because NQO1 can be targeted with β-lapachone, ‘unmasking’ the sensitivity of cancer to erastin." (PMID 37169843, 2023).
cancer (continued). "Synthetic analogues of seriniquinone are required due to its poor water solubility, with 10a and 10b showing strong PCCs of 0.75 and 0.72 to DPIQ anti-cancer activity, respectively, but weak to moderate PCCs of 0.47 and 0.48 to NQO1 expression, respectively." (PMID 37446864, 2023). "Elucidating NQO1’s precise functions within the context of oxidative stress and cancer has the potential to unravel novel avenues for therapeutic innovations and deepen our understanding of cellular adaptation to stress conditions." (PMID 38264080, 2023). "While most research has described the biological function of NQO1 in certain types and limited samples, a comprehensive understanding of the NQO1’s function and clinical importance at the pan-cancer level is scarce." (PMID 37583897, 2023). "These estrogen-mediated factors can enhance the effects of cancer therapy in women by reducing the activation of the NQO1 transcription factor NRF2 and regulating other antioxidant-related transcription factors via the NRF2 pathway." (PMID 37583897, 2023). "More research is needed to understand the role of NQO1 in tumor infiltration, and immune checkpoint inhibitors in various cancers are needed." (PMID 37583897, 2023). "To better understand the role of NQO1 in promoting cancer cell proliferation, we dissociated spheroid cultures and monitored their growth in two-dimensional culture." (PMID 36980879, 2023). "In the late 1980s, our laboratory commenced studies on β-lap (clinically formulated as ARQ761), a notable naphthoquinone due to its selective cytotoxicity towards NQO1-overexpressing cancer cells." (PMID 38136388, 2023). "When the Keap1/NRF2 pathways, influenced by cancer-promoting signals, become disrupted in cancer cells, there is a surge in the transcription and translation of NQO1." (PMID 38264080, 2023). "NQO1 has a “Janus” effect in cancer biology, where it behaves as either a tumour suppressor or a tumour promotor, with the former based on the prevention of SET processes that lead to an accumulation of harmful ROS." (PMID 37446864, 2023). "In view of the previous finding that CKS1 (encoded by CKS1B) is associated with cell cycle progression from G2 phase to M phase 50, we explored the pathway by which NQO1 regulates CKS1B to promote progression from G2 phase to M phase in cancer cells." (PMID 36793872, 2023). "In the pan-cancer analysis, we observed the expression of NQO1 in 31 normal tissues extracted from the GTEx dataset." (PMID 37583897, 2023). "NQO1 is an oxidoreductase enzyme that catalyzes the direct two-electron reduction for various quinones, and it is upregulated in some human cancer tissues, such as non-small-cell lung carcinoma or pancreatic carcinoma." (PMID 38140069, 2023). "Treatment of NQO1+ cancer cells with a lethal dose of β-lap or DNQ alone induces PARP1 hyperactivation-mediated programmed necrosis (NAD+-Keresis)." (PMID 38136388, 2023). "Overall, this study showcases the incredible antitumor efficacy of IP-DNQ against NQO1-positive cancer cells." (PMID 38136388, 2023). "The cBioPortal (TCGA, Pan-Cancer Atlas) database was used to evaluate the pan-cancer alterations of the NQO1 gene." (PMID 37583897, 2023). "NQO1 is shown to be a protective and multifunctional antioxidant that regulates oxidative stress and DNA damage in chromatin-binding proteins in cancer cells." (PMID 37583897, 2023). "Mechanistically, IP-DNQ exterminates NQO1-positive cancer cells by generating excessive reactive oxygen species (ROS), thereby inducing DNA damage, PARP1 hyperactivation, and catastrophic energy loss." (PMID 38136388, 2023). "In this study, we systematically analyzed the role of NQO1 as a novel immunotherapeutic target in 33 cancers and found that NQO1 was closely related to immune infiltration." (PMID 37583897, 2023).
cancer (continued). "The present study systematically explored the expression levels and prognostic significance of NQO1 and the relationship of NQO1 with clinicopathological parameters and immune cell infiltration by pan-cancer and single-cell analysis." (PMID 37583897, 2023). "To confirm these findings, we transfected NQO1-expressing cancer cells with siCont and pCont, sic-Fos and pCont or sic-Fos and pCKS1B, and NQO1-deficient cancer cells with pCont and siCont, pc-Fos and siCont or pc-Fos and siCKS1B." (PMID 36793872, 2023). "We identified one antisense RNA that drives cancer progression by upregulating the redox enzyme NADPH quinone dehydrogenase 1 (NQO1), and named it NQO1-AS." (PMID 37169843, 2023). "The ability of NQO1 to generate cytotoxic hydroquinones can be a good therapeutic strategy to counteract cancer cell proliferation." (PMID 37175546, 2023). "Consistent with this, transfection with siCKS1B led to increased CDK1 kinase activity in NQO1-expressing cancer cells relative to siCont-transfected cells." (PMID 36793872, 2023). "siRNA-mediated knockdown of c-Fos in NQO1-expressing cancer cells increased CDK1 kinase activity, whereas overexpression of CKS1B decreased c-Fos-mediated enhancement of CDK1 kinase activity in these cells." (PMID 36793872, 2023). "Our data clearly demonstrate that KP372-1 + PARPi-enhanced tumor-selective toxicity occurs in NQO1+ cancer cells." (PMID 36203459, 2022). "In this case, high levels of NQO1 in cancer can help cancer cells to cope with the increased ROS just like normal cells, thus, tumor growth and metastasis is not only not compromised, but promoted." (PMID 35308531, 2022). "Multiplexed immunofluorescence, moreover, enabled us to measure NQO1 protein expression quantitatively on a single cell level of bronchial epithelial cells and cancer cells within each sample and across the cohort." (PMID 36359002, 2022). "While numerous studies have reported the beneficial effects of β-lap treatment against a wide variety of ailments, extensive research of NQO1 bioactivation has revealed strong anti-cancer effects of β-lap as well." (PMID 35893874, 2022). "The expression of NQO1 was significantly different between cancer and normal tissues in seventeen kinds of tumors." (PMID 36338728, 2022). "The downregulation of NQO1 by miR-494 has been shown to inhibit the Nrf2 signaling pathway, and we previously reported that miR-494 induces a quiescent state in cancer cells by suppressing oxidative phosphorylation." (PMID 36142607, 2022). "Due to its role in the antioxidant defense and stabilization of oncosuppressor proteins, it is likely that NQO1 play a role in cancer development." (PMID 36504709, 2022). "NQO1 has been confirmed to interact with interleukins in a variety of cancers, thereby affecting the inflammatory response and participating in the immune regulation associated with the tumor microenvironment." (PMID 34982796, 2022). "Therefore, contrasting experimental characterization and computational predictions can be challenging for current predictive tools and may help to improve them; 2) Altered NQO1 functionality is associated with increased risk of developing cancer and neurological disorders." (PMID 36504709, 2022). "Here, we show that KP372-1 combined with PARPi resulted in enhanced toxicity and synergistic killing of NQO1+ cancers through a robust ROS induction and enhanced DNA damage response." (PMID 36203459, 2022). "Induced NQO1 expression has also been shown to induce melanogenesis in cancer cell lines, with silenced expression having the opposite effect." (PMID 35326683, 2022). "NQO1 was first discovered to be inducible by a variety of compounds, and many of which showed cancer-fighting properties." (PMID 36338728, 2022). "Their modulation of ROS enzymes such as ubiquitin-specific protease-2 (USP2) and NADPH Quinone Oxidoreductase 1 (NQO1) gave them selectivity against cancer cells." (PMID 36500400, 2022).